CXCL13 (C-X-C motif chemokine ligand 13)
Diseases named in the same sentence as CXCL13 in open-access papers (continued):
Sharing a sentence is not in itself a finding about the gene and the disease.
breast cancer (continued). "Eight TFH genes (e.g., CXCL13, ICOS, SH2D1A, TIGIT, and PDCD1) have been reported as signatures in breast cancer, while TNFRSF17, a plasma cell signature, is said to be the gene signature of TLSs in ovarian cancer." (PMID 38612697, 2024). "The expression of CXCL13 and CXCR5 was significantly higher in breast cancer tissue than in normal breast tissues." (PMID 39001456, 2024). "Chemokine genes are commonly identified as TLS gene signatures, with 12 such genes identified in colorectal cancer, melanoma, hepatocellular carcinoma, and breast cancer (e.g., CCL2, CCL19, CXCL9, CXCL11, and CXCL13)." (PMID 38612697, 2024). "Of 321 formalin-fixed paraffin-embedded primary tumor tissue samples of patients with early breast cancer treated with chemotherapy, mRNA expressions of CXCL12, CXCL13, and CXCR5 were studied." (PMID 39001456, 2024). "In our previous study of transcriptome analysis of mammary tumors of PyMTSB2−/− mice, the expression levels of cancer immune modulated genes (ANXA3, CCL17, CXCL13, CXCR3, IFN-γ, NR4A1, and SEMA3a) were significantly changed." (PMID 38956496, 2024). "Based on the expression profiles of marker genes in these two subpopulations, we further developed a CD103+LAG3+ TIL-related prognostic model (CLTRP) based on CXCL13 and BIRC3 genes for predicting the prognosis of breast cancer patients." (PMID 37488535, 2023). "In present study, integrated analysis of scRNA-sequencing data derived from primary breast cancer and bulk RNA-sequencing data from patients receiving ICT identified CXCL13 and BIRC3 as TIL-related markers of ICT sensitivity in breast cancer." (PMID 37488535, 2023). "In RCB II/III breast cancer, univariate analysis showed that the TNM stage, EV_CXCL13 level, and EV_VEGF-A level were correlated with OS (p < 0.001, p = 0.023, and p = 0.026, respectively)." (PMID 37958571, 2023). "In breast cancer patients, tumor-infiltrating CD4+ lymphocytes were shown to be a vital source of CXCL13." (PMID 35844446, 2022). "Gene of Ccl17, Cxcl13, Cxcr3, IFN-γ, and Sema3a, were significantly decreased while the Anxa3 and Nr4a1 were significantly upregulated in SB2−/−;PyMT mammary tumors." (PMID 35768767, 2022). "Of interest, the results of a recent in vitro study have suggested that an anti‐CXCL13 antibody reduced the levels of activated ERK and cyclin D1 and potentiated the cleavage of caspase‐9, thereby reducing the viability of MDA‐MB‐231 breast cancer cells." (PMID 35702353, 2022). "It seems that there is a strong correlation between the CXCL13/CXCR5 axis and breast cancer progression, which have been verified in several studies." (PMID 35702353, 2022). "Except for CCL19, RAET1G, IL12B, CXCL13, CCL22, and NOS1 were significantly highly expressed in breast cancer at the mRNA level." (PMID 36292723, 2022). "Abnormally active CXCL13/CXCR5 signaling enhances cancer cell growth through complex and different mechanisms in breast cancer, intestinal cancer, lung cancer, prostate cancer, oral squamous cell carcinoma, renal cell carcinoma, neuroblastoma, and lymphoma." (PMID 35053457, 2022). "Previous studies have reported the crucial role of CXCL13 in follicular helper T cells and B cells recruitment, and intratumora CXCL13-producing CD4+ follicular helper T cells were relevant for prognosis in breast cancer." (PMID 34122408, 2021). "Breast cancer cells expressing CCL21 also recruit RORγt+ innate lymphoid cell group 3 (ILC3) to the TME, where ILC3 stimulates stromal cells to secrete CXCL13." (PMID 34947813, 2021). "CXCL13 is enriched in fibroblasts and CD8 + T cells in breast cancer, CD8 + Tex and CD4 + Tconv cells in colon cancer, and plasma in pancreatic cancer." (PMID 34439306, 2021). "CXCL13, originally named B cell attracting chemokine 1, is also identified to be correlated with CXCL9 (rho = 0.52, p < 0.001) in early breast cancer." (PMID 32963527, 2020).
breast cancer (continued). "Another elevated chemokine in the serum of breast cancer patients with brain metastases was CXCL13 (also known as B cell-attracting chemokine 1, BCA-1)." (PMID 32321535, 2020). "Mean serum concentrations of BCA-1 (CXCL13) and fractalkine (CX3CL1) were significantly higher in the sera of breast cancer patients with cerebral metastases compared to all other patient populations or controls." (PMID 32321535, 2020). "Only the sera of breast cancer patients with cerebral metastases had significantly increased levels of the cytokines fractalkine (CX3CL1) and BCA-1 (CXCL13)." (PMID 32321535, 2020). "The combination of the genes IFNG, CXCL13, CD30, and PRF1 clearly predicted favorable outcome in III and IV stage ovarian cancer and in basal-like breast cancer." (PMID 31998644, 2019). "Among the CXC chemokines, CXCL13, and its receptor, CXCR5, have been reported to be involved in the development of breast cancer, colon cancer, and lymphoma." (PMID 30723697, 2018). "Of them, a set of genes related to immune function, such as CXCL13, IGHM, IGLL3P, IGJ and IGKC, were up-regulated in young patients with breast cancer." (PMID 25990390, 2015). "Our data are in line with recent observation that co-expression of CXCL13 and CXCR5 in breast cancer patients closely correlates with tumor progression and lymph node metastasis." (PMID 25786345, 2015). "Using the data mining of gene expression profiles and the clinical sample-based validations, we first showed that CXCL13 was highly expressed in young breast cancer, and closely associated with some prognostic factors including lymph node positive and ER negative in young breast cancer." (PMID 25990390, 2015). "Further studies, however, are underway in our laboratory examining the exact consequences of CXCL13/CXCR5 interactions for the development and/or progression of breast cancer in vivo." (PMID 18781150, 2008). "Studies on the correlation between CXCL13 /CXCR5 signaling axis and gastric cancer, breast cancer, lung cancer and other tumors have been reported, but the correlation of CXCL13 /CXCR5 signaling axis in uterine adhesions remains unclear." (PMID 39456064, 2024). "CXCL13 was secreted by PD-1hiCD8+ T cells in lung cancer, by CD103+CD8+ cells in ovarian cancer, and by CXCR5–PD-1hiCD4+ follicular helper like T cells in breast cancer and nasopharyngeal cancer." (PMID 35552285, 2022). "Two groups of breast cancer datasets, GSE137356 and GSE18728, were used to determine if CXCL9 and CXCL13 expressions could predict chemotherapy response." (PMID 33815462, 2021). "Chronic hypoxia does not alter CXCL13 expression in breast cancer cells, hepatocarcinoma cells and lung adenocarcinoma cells." (PMID 33467722, 2021). "CXCL13 is secreted by TFH cells, and is involved in a positive feedback mechanism that enhances levels of memory, cytotoxic, T helper 1 (TH1), and TFH T cells, as well as B cells, in breast cancer." (PMID 33815462, 2021). "Along the same line, a study revealed high CXCL13 expression in primary tumors from Chinese young breast cancer patients (≤45 yo) but not in those from older women (≥65 yo)." (PMID 31354634, 2019). "To elucidate the prognostic role of different subsets of CD4+ T cells in early breast cancer, we focus here on the CD4+ cells, forkhead box P3 (FOXP3) + CD4+ regulatory T cells (Tregs), and C-X-C motif chemokine ligand 13 (CXCL13)-positive CD4+ follicular helper T (Tfh) cells." (PMID 29482642, 2018). "In a study on early breast cancer in which the patients had not received systemic treatment, presence of CXCL13 Tfh cells in cancer predicted longer survival and a high pCR rate after preoperative chemotherapy." (PMID 29482642, 2018). "Surprisingly, in this study, breast cancer overexpression of CXCL13 did not correlate with tumor infiltration by leukocytes but instead was immunohistochemically localized to the cytoplasm of the malignant epithelial cells." (PMID 20946665, 2010).
breast cancer (continued). "To this end, we analysed serum concentrations of CXCL13 protein in 44 healthy blood donors, 48 breast cancer patients without evidence of disease after surgical resection of their tumour, and 54 patients with metastatic breast cancer." (PMID 18781150, 2008). "Remarkably, in this quantitative assay, protein concentrations of CXCL13 in breast cancer samples almost approached the levels found in non-malignant inflamed tonsils, which served as a positive control." (PMID 18781150, 2008). "Unfortunately, the lack of CXCR5 surface expression on breast cancer cell lines did not allow for consequent functional analyses of the role of CXCL13 in breast cancer in vitro." (PMID 18781150, 2008). "However, we detected a strong and significant (P=0.0004) correlation between copy numbers of both genes analysed within breast cancer tissue, indicating a biologically relevant role of CXCR5 as a receptor for CXCL13 in this solid tumour." (PMID 18781150, 2008). "However, we observed a strong (P=0.0004) correlation between the expressions of CXCL13 and CXCR5 in breast cancer tissues, indicating a biologically relevant role of CXCR5 in vivo." (PMID 18781150, 2008). "Similarly, CXCL13/CXCR5 signaling can upregulate MMP-9 through the RANKL-Src axis, which other studies showed could facilitate lymph node metastasis in breast cancer." (PMID 40295829, 2025). "Additionally, an increase in serum CXCL13 concentration has been observed in patients with breast cancer who have metastasis compared to those without metastasis." (PMID 39344390, 2024). "Our data reveal fundamental differences between immune environments with and without exhausted T cells within luminal breast cancer, and show that expression of PD-1 and CXCL13 on T cells, and MHC-I – but not PD-L1 – on tumor cells are strong distinguishing features between these environments." (PMID 36609566, 2023). "Nonetheless, our analysis of the ENCODE Transcription Factor ChIP-Seq dataset in the UCSC Genome Browser revealed the CXCL13-neighbor phage sequence contains an experimentally-validated consensus binding site for the transcription factor FOXA1, a key mediator of hormonal response in breast cancer." (PMID 37082114, 2022). "In addition, expression levels of CXCL13 and CXCR5 could be potential biomarkers for diagnosis and prognosis for breast cancer." (PMID 35702353, 2022). "Additionally, a very recent study investigated the role of NRF2 in the transcriptional regulation of the chemokine CXCL13 and its receptor CXCR5, two known drivers of breast cancer cells migration and metastatic dissemination, from primary breast tumors to lymph nodes." (PMID 33805996, 2021). "This way, CXCL13 and its ligand might contribute significantly to tumour formation, and therapeutic interventions aiming at interrupting CXCL13/CXCR5 interactions might be of benefit for the clinical course of patients with breast cancer." (PMID 18781150, 2008). "Therefore, we favour the third possible explanation, suggesting that breast cancers cells might supply themselves with a growth advantage by the expression of CXCR5 and the release of CXCL13 in vivo." (PMID 18781150, 2008). "Although these findings, at first glance, do not support the concept of CXCR5 as the main target for CXCL13 overexpression in breast cancer, we believe that they do not reflect the potential role this chemokine receptor might play in vivo." (PMID 18781150, 2008). "Importantly, a concentration gradient- and time-dependent downregulation would also explain our observation of a strong correlation between CXCL13 expression and the presence of its receptor within breast cancer tissues despite the lack of CXCR5 overexpression in the same tissues." (PMID 18781150, 2008). "Previous analysis of serum from patients with breast cancer and cerebral metastases found increased levels of CX3CL1 and CXCL13 (levels of CCL2 among other chemokines were not elevated)." (PMID 37924145, 2023).
breast cancer (continued). "In addition, in a previous study, the expression profiles of CXCL12/CXCR4/CXCR7 and CXCL13/CXCR5 in the positive and negative LNs of breast cancer patients were found." (PMID 40584290, 2025).
autoimmune disease (65 papers, 2008 to 2026). A disorder resulting from loss of function or tissue destruction of an organ or multiple organs, arising from humoral or cellular immune responses of the individual to their own tissue constituents. "As the sole known ligand for CXCR5, which is expressed on mature B cells and Tfh cells, aberrant CXCL13 expression of CXCL13 in ectopic germinal centers has been implicated in various autoimmune diseases." (PMID 41567208, 2025). "We previously reported that chemokine CXCL13 — encoding a lymphocyte chemoattractant implicated in inflammatory conditions and autoimmune diseases — was the top differentially expressed gene in BPH versus normal prostate." (PMID 40178915, 2025). "Recent findings have suggested the pathogenic roles of the CXCL13/CXCR5 axis in autoimmune diseases, which indicates the potential role of CXCL13 as a disease biomarker and therapeutic target." (PMID 38911857, 2024). "CXCL13 has been implicated in the pathogenesis of several autoimmune diseases and even suggested as a potential therapeutic target for autoimmune disorders, including SLE." (PMID 38098483, 2023). "Recently, CXCL13 chemokine was reported to be associated with the pathogenesis of various autoimmune diseases (for instance, primary Sjogren syndrome, rheumatoid arthritis, multiple sclerosis, and systemic lupus erythematosus)." (PMID 37628716, 2023). "High CXCL13 gene expression was associated with disease activity and pathogenicity in autoimmune diseases, such as RA, and with patients’ prognosis in several types of cancer, implying the strong involvement of CXCL13-dependent TLS formation." (PMID 35552285, 2022). "In this review, we discuss the biological features of CXCL13 and CXCR5 and the recent findings on the pathogenic roles of the CXCL13/CXCR5 axis in autoimmune diseases." (PMID 35309354, 2022). "In this review, we provide a comprehensive overview of the pathogenic role of CXCL13/CXCR5 axis in autoimmune diseases, while also discussing the potential usage of CXCL13 as a novel clinical biomarker and treatment target." (PMID 35309354, 2022). "CXCL13 has been mechanistically linked to several disorders, including autoimmune diseases and hematologic malignancies." (PMID 34484201, 2021). "CXCL13, as a B lymphocyte chemoattractant, has been widely implicated in the pathogenesis of inflammatory conditions and autoimmune diseases, which preferentially promoted the migration and chemotaxis of B lymphocytes by stimulating calcium influx." (PMID 33679883, 2021). "CXCL13 in module 1, related to the chemokine signalling pathway, has been linked to joint inflammation and the development of autoimmune disorders, including RA." (PMID 31178673, 2019). "In parallel, we observed increased levels of CXCL13 in the serum of Tg mice similar to increased CXCL13 serum levels in autoimmune diseases associated with cell infiltrations in divers organs and even ectopic GCs." (PMID 26771137, 2016). "Aberrant expression of CXCL13 within ectopic germinal centers has been linked to the development of autoimmune disorders (e.g. Rheumatoid Arthritis, Multiple Sclerosis, Systemic Lupus Erythematosis)." (PMID 25879435, 2015). "CXCL13, a B-cell chemokine produced mainly by mesenchymal lymphoid tissue organizer cells, follicular dendritic cells, and human T follicular helper cells, was found to be linked to a number of autoimmune diseases, including ITP." (PMID 37045944, 2023). "CXCL13 is also associated with immunodeficiency associated autoimmune diseases such as CVID." (PMID 35309354, 2022). "Originally identified as a B-cell chemoattractant, CXCL13 exerts important functions in lymphoid neogenesis, and has been widely implicated in the pathogenesis of several autoimmune diseases and inflammatory conditions, as well as in lymphoproliferative disorders." (PMID 34746181, 2021). "CXCL13 is associated with the progression of autoimmune diseases, including RA." (PMID 34518512, 2021).
autoimmune disease (continued). "Originally identified as a B-cell chemoattractant, CXCL13 exerts important functions in lymphoid neogenesis, and has been widely implicated in the pathogenesis of a number of autoimmune diseases and inflammatory conditions, as well as in lymphoproliferative disorders." (PMID 31354634, 2019). "CXCL13, initially identified as a B-cell chemoattractant, exerts essential functions in lymphoid neogenesis and has been widely implicated in the pathogenesis of several autoimmune diseases and inflammatory conditions, as well as in lymphoproliferative disorders." (PMID 33816243, 2021). "The CXCR5 receptor is a candidate receptor for CXCL13 that regulates various biological processes, including nerve regeneration, the inflammatory response, autoimmune diseases and cancer." (PMID 40325003, 2025). "CXCL13 is the only ligand for CXCR5 and the CXCL13/CXCR5 axis is associated with the development of tumors, autoimmune diseases, infectious diseases, and many other diseases." (PMID 37382265, 2023). "The pivotal role CXCL13/CXCR5 axis in ELSs development has been detected in several autoimmune diseases such as RA and pSS." (PMID 35309354, 2022). "CXCL13 has been observed to be expressed in the meninges of the CNS during autoimmune diseases and has emerged as a candidate as a therapeutic target for multiple sclerosis (MS) due to its role in myelinating glial cells." (PMID 35624463, 2022). "In brief, although numerous challenges remain, CXCL13/CXCR5 axis is undoubtedly a promising therapeutic target for human autoimmune diseases." (PMID 35309354, 2022). "CXCL13 is a chemokine that is widely involved in the pathogenesis of autoimmune diseases, tumors and inflammatory diseases." (PMID 36172372, 2022). "CXCL13 has been reported to play a major role in the pathogenesis of several autoimmune diseases, lymphoproliferative disorders, inflammatory conditions, as well as lymphoid neogenesis." (PMID 35457267, 2022). "This review highlights the biological functions, protein structures, signaling transduction pathways, and roles of CXCL13/CXCR5 in the pathogenesis of autoimmune diseases." (PMID 35309354, 2022). "In this context, the role of CXCL13 as a B-cell chemokine and key regulator of humoral immunity has attracted considerable attention in the study of the development of autoimmune diseases." (PMID 35309354, 2022). "Clinical studies have shown that CXCL13 expression is elevated in autoimmune diseases patients, and is correlated with clinical parameters that are related to disease severity, activity, and prognosis." (PMID 35309354, 2022). "Dysregulation of the CXCL13 affecting both B cells and T follicular helper cells function was a major player in autoimmune disorders." (PMID 35058922, 2021). "Studies have evaluated the expression of B cell marker CXCL13 and found that CXCL13 is elevated in a variety of autoimmune diseases, including SS." (PMID 34660815, 2021). "Inhibiting the CXCL13/CXCR5-mediated signaling pathway is a new direction for the treatment of autoimmune disorders." (PMID 34518512, 2021). "CXCL13, a B-lymphocyte chemokine, is widely involved in the pathogenesis of inflammatory and autoimmune diseases and preferentially promotes B-lymphocyte migration and chemotaxis by stimulating calcium inward flow." (PMID 35047401, 2021). "Specifically, BLC, also known as CXCL13, has been reported to be highly expressed in many autoimmune diseases, leading to abnormal lymphocyte recruitment and tissue damage." (PMID 34249954, 2021). "This is in agreement with previous findings linking local and systemic autoimmune responses in pSS, as well as relevant findings in other autoimmune diseases suggesting that CXCL13 serum levels reflect the local inflammation in the affected organs." (PMID 34484201, 2021). "Relatedly, experimental anti-CXCL13 antibodies have shown promising results on murine models of autoimmune disease." (PMID 30984195, 2019).